DLG5 (discs large MAGUK scaffold protein 5)
Description:
Acts as a regulator of the Hippo signaling pathway. Negatively regulates the Hippo signaling pathway by mediating the interaction of MARK3 with STK3/4, bringing them together to promote MARK3-dependent hyperphosphorylation and inactivation of STK3 kinase activity toward LATS1. Positively regulates the Hippo signaling pathway by mediating the interaction of SCRIB with STK4/MST1 and LATS1 which is important for the activation of the Hippo signaling pathway. Involved in regulating cell proliferation, maintenance of epithelial polarity, epithelial-mesenchymal transition (EMT), cell migration and invasion. Plays an important role in dendritic spine formation and synaptogenesis in cortical neurons; regulates synaptogenesis by enhancing the cell surface localization of N-cadherin. Acts as a positive regulator of hedgehog (Hh) signaling pathway. Plays a critical role in the early point of the SMO activity cycle by interacting with SMO at the ciliary base to induce the accumulation of KIF7 and GLI2 at the ciliary tip for GLI2 activation (By similarity).
Synonyms: KIAA0583; PDLG; P-dlg; LP-DLG; P-DLG5; YUVOB
Tractability: Antibody: UniProt places it where antibodies can reach, with high confidence; its Gene Ontology location is reachable by antibodies, with high confidence. PROTAC: ubiquitination databases record sites on it; its protein half-life has been measured.
Gene: Protein-coding gene on chromosome 10 (77,790,778 to 77,927,220, reverse strand). Ensembl gene ENSG00000151208.
Subcellular location: Cell junction; Cell membrane; Postsynaptic density; Cytoplasm, cytoskeleton, cilium basal body
Subcellular location (Human Protein Atlas): Cell Junctions
Pathways (Reactome):
Signal Transduction: RHOU GTPase cycle; RHOV GTPase cycle; RND1 GTPase cycle; RND2 GTPase cycle; RND3 GTPase cycle
Gene Ontology:
Molecular function: beta-catenin binding; cytoskeletal protein binding; protein binding; signaling receptor complex adaptor activity
Biological process: epithelial to mesenchymal transition; maintenance of cell polarity; negative regulation of cell migration; negative regulation of hippo signaling; negative regulation of T cell proliferation; positive regulation of hippo signaling; cell-cell adhesion; establishment or maintenance of epithelial cell apical/basal polarity; intracellular signal transduction; negative regulation of cell population proliferation; positive regulation of dendritic spine development; positive regulation of smoothened signaling pathway; positive regulation of synapse assembly; signal transduction; animal organ development; cell differentiation; establishment or maintenance of cell polarity; positive regulation of signal transduction; postsynapse organization; regulation of apoptotic process; regulation of multicellular organismal process; tissue development
Cellular component: anchoring junction; cell junction; adherens junction; ciliary basal body; cytoplasm; plasma membrane; postsynaptic density; glutamatergic synapse
Genetic constraint (gnomAD): Loss-of-function variants: 48 observed, 183.1 expected, observed/expected ratio (o/e) 0.26, 90% interval 0.21 to 0.33. The upper end of that interval is the gene's LOEUF score, 0.33, which puts it in group 1 of 6, group 1 being the genes least tolerant of losing a copy. Missense variants: 2,154 observed, 2,557.3 expected, observed/expected ratio (o/e) 0.84, 90% interval 0.81 to 0.87. Synonymous variants: 1,013 observed, 1,047 expected, observed/expected ratio (o/e) 0.97, 90% interval 0.92 to 1.02.
Homologues: Orthologues: chimpanzee DLG5 (99% identical), macaque DLG5 (98% identical), pig DLG5 (95% identical), dog DLG5 (94% identical), mouse Dlg5 (92% identical), rat Dlg5 (91% identical), guinea pig DLG5 (87% identical), tropical clawed frog dlg5 (63% identical), zebrafish dlg5a (60% identical), zebrafish dlg5b.1 (52% identical), rabbit DLG5 (51% identical), Drosophila melanogaster Dlg5 (26% identical), and 1 more. Paralogues in human: TJP1 (12% identical), TJP2 (12% identical), TJP3 (10% identical).
Diseases named in the same sentence as DLG5 in open-access papers:
DLG5 is named in the same sentence as 48 diseases in open-access papers, as found by Europe PMC text mining. Sharing a sentence is not in itself a finding about the gene and the disease. The quoted sentences say what the papers report.
breast carcinoma (9 papers, 2017 to 2023). "We are interested in further investigating the molecular mechanisms underlying the action of DLG5 in regulating TAZ expression in ER+ breast cancer." (PMID 30450766, 2019). "Taken together, loss of DLG5 expression promoted breast cancer malignancy by inactivating the Hippo pathway and increasing nuclear YAP." (PMID 28169360, 2017). "In summary, loss of DLG5 expression promoted breast cancer malignancy by inactivating the Hippo signaling pathway and increasing nuclear YAP." (PMID 28169360, 2017). "In this study, we showed that loss of DLG5 promoted breast cancer cell proliferation by inhibiting the Hippo signaling pathway and increasing nuclear YAP expression." (PMID 28169360, 2017). "To summarize, stage I and stage II breast cancer tissues demonstrated reduced DLG5 staining, while stage III tissues showed loss of or reduced DLG5 staining." (PMID 28169360, 2017). "In addition, we showed that DLG5 expression is positively associated with ER/PR status, an important indicator for breast cancer therapy and prognosis." (PMID 28169360, 2017). "The results suggest that DLG5 might be associated with breast cancer therapy and prognosis." (PMID 28169360, 2017). "In support of this possibility, we demonstrated that silencing of either DLG5 or PRDM16 abolished multiple LINC00589-induced effects in HER2-positive breast cancer." (PMID 36309503, 2022). "DLG5 has been shown to be lost in breast cancer cells with restoration of DLG5 expression inhibiting cell migration and proliferation." (PMID 33726762, 2021). "DLG5 expression was downregulated in many human cancers, such as bladder cancer, prostate cancer, breast cancer, and hepatocellular carcinoma, not only that, knockdown of DLG5 significantly increased cell migration and invasion in these cancers." (PMID 32015336, 2020). "DLG5 downregulation increases the frequency of breast cancer cells with stem-like properties, through an effect mediated by TAZ induction." (PMID 32210163, 2020). "Taken together, our data indicate that down‐regulated DLG5 expression increases the stemness of breast cancer cells by enhancing TAZ expression, contributing to TAM resistance in breast cancer." (PMID 30450766, 2019). "A genome wide RNAi screen showed that DLG5 contributes to invasion and metastasis in breast cancer cell." (PMID 31856229, 2019). "Together, such data indicated that down‐regulated DLG5 promoted TAM resistance of breast cancer by promoting TAZ expression and nuclear translocation." (PMID 30450766, 2019). "Here, we show that discs large homolog 5 (DLG5) expression is down‐regulated in TAM‐resistant breast cancer and cells." (PMID 30450766, 2019). "In breast cancer, knockdown of DLG5 induces cell migration, and overexpression of DLG5 inhibits cell migration." (PMID 28169360, 2017). "DLG5 was highly expressed in normal breast tissues/cells and low-grade breast cancer tissues/cells, but its expression was reduced or lost in high-grade breast cancer tissues/cells." (PMID 28169360, 2017). "To identify the relationship between DLG5 and breast cancer, we examined the expression of DLG5 in breast cancer tissues." (PMID 28169360, 2017). "DLG5 expression was higher in breast cancer cell lines of the luminal subtype than in those of the basal-like subtype." (PMID 28169360, 2017). "To investigate the role of DLG5 in EMT in breast cancer cells, we compared the expression of EMT makers in MCF10A-shDLG5, MCF7-shDLG5 and NC cells." (PMID 28169360, 2017). "DLG5 expression progressively decreased in primary breast cancer samples from stage I to stage III." (PMID 32210163, 2020). "Conceivably, the inhibition of TAZ or the enhancement of DLG5 expression may be valuable for the restoration of TAM sensitivity in TAM‐resistant ER+ breast cancers." (PMID 30450766, 2019). "Our findings support the notion that DLG5 enhances the sensitivity to TAM in ER+ breast cancer." (PMID 30450766, 2019).
breast carcinoma (continued). "DLG5 expression showed a significant positive correlation with ER and PR status in breast cancer." (PMID 28169360, 2017). "Taken together, loss of DLG5 expression induced partial EMT and enhanced cell migration and invasion; DLG5 might also be involved in regulating the metastatic progression of breast cancer." (PMID 28169360, 2017). "DLG5 showed stronger staining in normal mammary tissues than in breast cancer tissues." (PMID 28169360, 2017). "Obviously, DLG5 is closely related to breast cancer development." (PMID 28169360, 2017). "Hence, altered DLG5 expression modulated the sensitivity of breast cancer cells to TAM in vitro." (PMID 30450766, 2019). "We are the first to report that loss of DLG5 increased YAP nuclear localization, inhibited YAP degradation, down-regulated Scribble expression, and mislocalized Scribble from the membrane to the cytoplasm; these findings provide insight into the mechanism underlying breast cancer progression." (PMID 28169360, 2017). "To confirm the roles of DLG5 and PRDM16 in LINC00589-regulated CSC-like properties and multiple chemoresistance of breast cancer, we performed mammosphere formation and cell viability assays." (PMID 36309503, 2022). "A recent study showed the existence of a connection between DLG5 and YAP in breast cancer development and progression." (PMID 32210163, 2020). "DLG5 silencing decreased the sensitivity to TAM and increased the frequency and stemness of CD44+/CD24− breast cancer stem cells (BCSCs) and TAZ, a transducer of the Hippo pathway, expression in MCF7 cells while DLG5 overexpression had opposite effects." (PMID 30450766, 2019). "Our data indicated that down‐regulated DLG5 expression increased the breast cancer stem cell‐like characteristics by enhancing TAZ expression, contributing to TAM resistance in ER+ breast cancer." (PMID 30450766, 2019). "A non-transformed breast epithelial cell line (MCF10A) and low-grade breast cancer cell lines (MCF7, T47D and BT474) showed higher DLG5 protein and mRNA expression levels than high-grade breast cancer cell lines (MDA-MB-468, MDA-MB-231 and MDA-MB-453)." (PMID 28169360, 2017). "Nearly 76% of stage I breast cancer, 55% of stage II breast cancer, and 23% of stage III breast cancer samples showed moderate or strong DLG5 staining." (PMID 28169360, 2017). "Similarly, deletion of discs large homolog 5 (DLG5) in breast cancer cell lines inhibits the Hippo signaling pathway and increases YAP expression in the nucleus, thus promoting breast cancer cell proliferation, migration, and invasion." (PMID 37256184, 2023). "In this study, we examined DLG5 expression in paired of TAM‐sensitive and resistant breast cancer tissues and employed TAM‐sensitive and resistant ER+ breast cancer cells to determine the effect of altered DLG5 expression on TAM sensitivity, apoptosis and stemness as well as TAZ expression." (PMID 30450766, 2019). "In summary, our data indicated that DLG5 expression was down‐regulated in ER+ TAM‐resistant breast cancer tissues and cells, and DLG5 silencing increased the resistance to TAM and breast cancer cell stemness by enhancing TAZ expression and nuclear translocation in ER+ breast cancer cells." (PMID 30450766, 2019). "We intend to verify the connection of DLG5 and YAP in breast cancer development." (PMID 28169360, 2017). "Our study revealed that knockdown of endogenous DLG5 inhibited the Hippo signaling pathway, induced EMT, disrupted epithelial cell polarity, and enhanced cell migration and invasiveness, thereby promoting breast cancer malignancy." (PMID 28169360, 2017). "Hence, DLG5 inhibited TAZ expression and nuclear translocation in breast cancer cells." (PMID 30450766, 2019). "Therefore, DLG5 and TAZ may be valuable therapeutic targets for control of TAM resistance in ER+ breast cancer." (PMID 30450766, 2019).
breast carcinoma (continued). "Moreover, IHC assay demonstrated low expression of DLG5 and PRDM16 in trastuzumab non-response HER2-positive breast cancer patients but high expression of DLG5 and PRDM16 in trastuzumab-response HER2-positive breast cancer patients." (PMID 36309503, 2022).
Hydrocephalus (9 papers, 2008 to 2025). Hydrocephalus is an active distension of the ventricular system of the brain resulting from inadequate passage of CSF from its point of production within the cerebral ventricles to its point of absorption into the systemic circulation. "Dysregulated YAP signaling is also associated with hydrocephalus pathogenesis through different causes, such as Dlg5 mutants and posthemorrhagic hydrocephalus induced by lysophosphatidic acid (LPA) injection." (PMID 39936032, 2025). "In both mouse and Xenopus, loss of DLG5 leads to hydrocephaly; however, at least in Xenopus, ventricular flow appears somewhat intact based on OCT imaging." (PMID 32631816, 2021). "Patients with variants of DLG5 were found to have a variety of phenotypes including cystic kidneys, nephrotic syndrome, hydrocephalus, limb abnormalities, congenital heart disease and craniofacial malformations." (PMID 32631816, 2021). "Further, DLG5 (Dlg5) maintains polarity of epithelial cells, and Dlg5-/- mice cause hydrocephalus." (PMID 40459058, 2025). "From these results, we conclude that dlg5 is critical for multiple phenotypes in the embryo including hydrocephalus and kidney abnormalities, likely due to a functional role for Dlg5 in ciliated cells." (PMID 32631816, 2021). "Mislocalization of β-Catenin and N-cadherin was also observed in Dlg5 mutant mice that manifest obstructive hydrocephalus." (PMID 18928559, 2008). "Dlg5 gene knockout mice exhibit hydrocephalus and renal cysts." (PMID 35361250, 2022). "Consistent with a loss-of-function allele, the DLG5 sequence variant identified in a proband with hydrocephalus (p.Arg821Ter) did not significantly improve the ventricular size caused by Dlg5 depletion." (PMID 32631816, 2021). "Dlg5 knockout (−/−) mice have penetrant hydrocephalus and kidney cysts." (PMID 22539977, 2012).
Crohn disease (8 papers, 2008 to 2021). A gastrointestinal disorder characterized by chronic inflammation involving all layers of the intestinal wall, noncaseating granulomas affecting the intestinal wall and regional lymph nodes, and transmural fibrosis. "Dlg5 has been described as a susceptibility gene for Crohn's disease, one of two subphenotypes of inflammatory bowel disease, although the involvement of this gene in this disease is still controversial." (PMID 22539977, 2012). "Recent reports have shown that polymorphisms in Dlg5 are associated with Crohn's disease in a gender- and age-specific manner." (PMID 22539977, 2012). "Many genetic variants in DLG5 are significantly associated with Crohn's disease susceptibility." (PMID 34962722, 2021). "Dlg5 has been reported to be one of the susceptibility genes for Crohn's disease." (PMID 22539977, 2012). "Dlg5 has been described as a susceptibility gene for Crohn's disease; however, the physiological function of Dlg5 is unknown." (PMID 22539977, 2012). "No SNPs were confirmed for the CARD15/NOD2 gene fragment, but a substitution (T>C) was found in the DLG5 gene in a Crohn's disease patient." (PMID 30648106, 2018). "The analysed variants of the CARD15/NOD2 and DLG5 genes can significantly contribute to the development of IBD, i.e., Crohn's disease and ulcerative colitis." (PMID 30648106, 2018). "Genetic variants in DLG5 (a human homolog of C. elegans dlg-1 and Drosophila dlg) are associated with IBD, and intestinal permeability has been correlated with peripheral immune activation and clinical relapse in patients with Crohn’s disease." (PMID 26769134, 2016). "The study suggests that SNPs (T>C substitution) affect the function of the DLG5 protein and thus play a role in the development of IBD, in particular Crohn's disease." (PMID 30648106, 2018). "Thus, Dlg5 may also affect the pathology of Crohn's disease via regulation of TGF-β signaling." (PMID 22539977, 2012).
hepatocellular carcinoma (4 papers, 2019 to 2022). A malignant tumor that arises from hepatocytes. "Dlg5 was down-regulated in hepatocellular carcinoma (HCC) and lower Dlg5 expression was associated with poor survival of HCC patients." (PMID 31787846, 2019).
Renal cyst (4 papers, 2019 to 2025). A fluid filled sac in the kidney. "Dlg5 knockout mice exhibited cerebral aqueduct occlusion, severe brain edema, renal cysts, emphysema-like lesions, and half of these mice were dead during perinatal." (PMID 31787846, 2019). "Seven genes (3%) had no entries in OMIM (DLG5 in renal ciliopathies and cystic kidney diseases; and 6 in the proteinuric kidney diseases [APOE, DLC1, FAT1, ITSN1, PODXL and TNS2]) and were excluded." (PMID 40303230, 2025).
bladder cancers (3 papers, 2019 to 2020). "The down-regulation of Dlg5 has been implicated in the malignancy of breast, prostate, bladder cancers and HCC." (PMID 31787846, 2019). "DLG5 is a cell polarity gene and its downregulation has been implicated in the malignancy of breast, prostate and bladder cancers." (PMID 31277598, 2019).
ciliopathy (3 papers, 2021 to 2023). A genetic disorder of the cellular cilia or the cilia anchoring structures, the basal bodies, or of ciliary function. "Here, in a cohort of four unrelated families, we describe an association of discs large 5 (DLG5) with multiple different patient phenotypes including those associated with ciliopathies." (PMID 32631816, 2021). "Interestingly, DLG5 variants are associated with ciliopathy-like phenotypes and congenital anomalies, and depletion of Xenopus dlg5 disrupts brain ventricle and kidney morphology." (PMID 35997111, 2022). "Our work establishes DLG5 as a ciliopathy gene that can present with a variety of different phenotypes." (PMID 32631816, 2021). "DLG5 is essential for cilia and many of the patient phenotypes are in the ciliopathy spectrum." (PMID 32631816, 2021).
colorectal cancer (3 papers, 2008 to 2025). A primary or metastatic malignant neoplasm that affects the colon or rectum. "This study identified and validated a reproducible five-gene panel—DLG5, CD177, SH2D1B, NQO2, and KRT73—derived from whole-blood RNA, with strong diagnostic relevance for colorectal cancer (CRC)." (PMID 41373777, 2025). "In the present study, we compared the frequency of a series of polymorphisms in different inflammatory response genes associated with IBD (DLG5, IL-4, OCTN, TNFα and NOD2) in colorectal cancer cases against controls." (PMID 18433468, 2008). "Ten SNPs in the following six genes: NOD2 (2140 C/T, 2722 G/C), DLG5 (113 G/A), OCTN1 (1672 C/T), OCTN2 (-207 G/C), IL4 (-590 C/T) and TNFα (-308 G/A, -857 C/T, -863 C/A, -1031 T/C) were screened in a consecutive series of colorectal cancer patients using a two-staged approach." (PMID 18433468, 2008).
emphysema (3 papers, 2008 to 2021). "Moreover, previous studies have reported that DLG5 downregulation leads to emphysema‐like lesions, indicating that DLG5 might function in respiratory diseases." (PMID 34962722, 2021).